MAU2 (MAU2 sister chromatid cohesion factor)
Description:
Plays an important role in the loading of the cohesin complex on to DNA. Forms a heterodimeric complex (also known as cohesin loading complex) with NIPBL/SCC2 which mediates the loading of the cohesin complex onto chromatin. Plays a role in sister chromatid cohesion and normal progression through prometaphase.
Synonyms: MAU-2; KIAA0892; SCC4; MGC75361; MAU2L; CDLS7
Tractability: PROTAC: ubiquitination databases record sites on it; its protein half-life has been measured.
Gene: Protein-coding gene on chromosome 19 (19,320,811 to 19,358,754, forward strand). Ensembl gene ENSG00000129933.
Subcellular location: Nucleus, nucleoplasm; Nucleus; Chromosome
Subcellular location (Human Protein Atlas): Nucleoplasm; Nuclear bodies
Pathways (Reactome):
Cell Cycle: Cohesin Loading onto Chromatin
Gene Ontology:
Molecular function: cohesin loader activity; protein binding
Biological process: maintenance of mitotic sister chromatid cohesion; mitotic sister chromatid cohesion; chromatin looping
Cellular component: chromatin; nuclear body; nucleoplasm; nucleus; Scc2-Scc4 cohesin loading complex; SMC loading complex; chromosome
Genetic constraint (gnomAD): Loss-of-function variants: 8 observed, 82.51 expected, observed/expected ratio (o/e) 0.097, 90% interval 0.056 to 0.17. The upper end of that interval is the gene's LOEUF score, 0.17, which puts it in group 1 of 6, group 1 being the genes least tolerant of losing a copy. Missense variants: 415 observed, 788.48 expected, observed/expected ratio (o/e) 0.53, 90% interval 0.49 to 0.57. Synonymous variants: 349 observed, 339.64 expected, observed/expected ratio (o/e) 1.03, 90% interval 0.94 to 1.12.
Homologues: Orthologues: macaque MAU2 (99% identical), rat Mau2 (99% identical), dog MAU2 (99% identical), guinea pig MAU2 (99% identical), mouse Mau2 (96% identical), chimpanzee MAU2 (96% identical), pig MAU2 (95% identical), rabbit MAU2 (94% identical), tropical clawed frog mau2 (93% identical), zebrafish mau2 (66% identical), Drosophila melanogaster Mau2 (48% identical), Caenorhabditis elegans mau-2 (20% identical).
Diseases named in the same sentence as MAU2 in open-access papers:
MAU2 is named in the same sentence as 33 diseases in open-access papers, as found by Europe PMC text mining. Sharing a sentence is not in itself a finding about the gene and the disease. The quoted sentences say what the papers report.
Cornelia de Lange syndrome (9 papers, 2013 to 2026). A rare syndrome characterized by low birth weight, delayed growth, intellectual disabillity, behavioral problems, and a distinctive facial appearance (thin, arched eyebrows, low set ears, small teeth, and small nose). "While NIPBL variants are a major cause of Cornelia de Lange Syndrome (CdLS), the role of MAU2 in disease is unclear." (PMID 41912533, 2026). "According to recent research, MAU2, a protein-coding gene, has a significant role in chromatin-related functions such as DNA repair and regulation of transcription and has been associated with headache and the rare condition Cornelia de Lange Syndrome." (PMID 36808568, 2023). "Mutations of MAU2 have been linked with a rare disorder of Cornelia de Lange Syndrome." (PMID 36939796, 2023). "Similarly, the equivalent patch on the Scc4 ortholog, MAU2, mediates cohesin recruitment to chromosomes in Xenopus extracts, and a small deletion of this region in human MAU2 causes the developmental disorder Cornelia de Lange syndrome." (PMID 39690240, 2025). "A single NIPBL missense mutation, derived from a Cornelia de Lange Syndrome (CdLS) patient, prevents a 300-amino-acid NIPBL fragment from binding MAU2." (PMID 28167679, 2017). "Pathogenic variants in NIPBL, MAU2, SMC1A, SMC3, RAD21, and HDAC8 cause Cornelia de Lange syndrome (CdLS), a multisystem disorder characterized by intellectual disability, facial dysmorphism, growth delay, and upper limb anomalies." (PMID 41492387, 2025). "Mutations in MAU2 and NIPBL, the human cohesin loader subunits, are the cause of Cornelia de Lange Syndrome (CdLS), a hereditary disorder whose clinical features are thought to be the consequence of subtle gene expression changes in numerous developmental genes." (PMID 36509793, 2022).
hyperlipidemia (3 papers, 2020 to 2026). "Several SNPS, such as rs11591147 in PCSK9, rs1260326 in GCKR, rs10455872 in LPA, rs964184 in ZPR1, rs58542926 in TM6SF2, and rs182611493 in MAU2 have been clinically associated with multiple metabolic disorders, including coronary heart disease, hyperlipidemia, non-alcoholic fatty liver disease." (PMID 41608459, 2026). "The genotypic and allelic frequencies of 12 SNPs in the NCAN, TM6SF2, CILP2, PBX4, SUGP1 and MAU2 were substantially different between the hyperlipidemia and normal groups." (PMID 32568739, 2020). "In conclusion, this study shows potential interactions among the NCAN, TM6SF2, CILP2, PBX4, SUGP1 and MAU2, environment and serum lipid levels in hyperlipidemia subjects." (PMID 32568739, 2020). "The incidences of the NCAN C-C (G2), TM6SF2 T-A (G3), TM6SF2 C-A (G5), CILP2 G-T (G6), PBX4-SUGP1 G-C (G8), MAU2 G-G-G-C (G9), MAU2 G-A-G-C (G10), MAU2 C-G-A-T (G12), and MAU2 C-A-G-T (G13) haplotypes were significantly different between the hyperlipidemia and normal groups (P < 0.05 for all)." (PMID 32568739, 2020). "The haplotype-haplotype interaction showed that G10 (MAU2 G-A-G-C) and G6 (CILP2 G-T) carriers could reduce the risk of hyperlipidemia compared with G10 or G6 carriers." (PMID 32568739, 2020).
Hepatic steatosis (2 papers, 2025 to 2026). Steatosis is a term used to denote lipid accumulation within hepatocytes. "MAU2, a component of the chromosomal condensin complex, has been associated with hepatic steatosis in normal-weight individuals through its genetic variants." (PMID 41056021, 2026). "Currently, there is limited mechanistic evidence linking MAU2 to hepatic steatosis or metabolic dysfunction." (PMID 40677695, 2025).
acute myeloid leukemia (1 paper, 2022). Acute myeloid leukemia (AML) is a group of neoplasms arising from precursor cells committed to the myeloid cell-line differentiation. "For example, somatic mutations in the eight genes that comprise the cohesin ring (SMC1A, SMC3, STAG1, STAG2, RAD21) and the cohesin-ring support genes (NIPBL, MAU2, WAPL, PDS5A, PDS5B) and CTCF are frequently found in many cancer types and are especially common in acute myeloid leukemia (AML)." (PMID 36171609, 2022).
dyslipidemia (1 paper, 2020). "However, the relationship between dyslipidemia and SUGP1 and MAU2 is not clear in the Chinese populations, and the association between SNPs, gene-gene, and gene-environment interactions and dyslipidemia is still limited." (PMID 32568739, 2020).
Intellectual disability (1 paper, 2025). "Associations with intellectual disability include rs78294462 in TCF4, rs376456 and rs1009136 in MAU2, and rs7200247 in GLG1." (PMID 40282399, 2025).
liver cancer (1 paper, 2022). An epithelial or non-epithelial malignant neoplasm that arises from the liver. "The results of our study may also reveal the role of the cohesin subunit of MAU2 in liver cancer." (PMID 35646080, 2022).
migraine (1 paper, 2023). "Among the overlapping genes, four (ADAMTSL4, EHMT2, SUGP1, and MAU2) were associated with migraine, headache, and at least five glycemic traits." (PMID 36808568, 2023).
steatosis (1 paper, 2025). Increased lipid within the cytoplasm of cells. "In addition, GWAS fine mapping identified potential causal variants in GATAD2A, SUGP1, and MAU2, while TWAS fine mapping implicated SAMM50 as a driver of steatosis in normal-weight individuals, possibly through changes in gene expression." (PMID 40677695, 2025).
cancer (9 papers, 2014 to 2025). A tumor composed of atypical neoplastic, often pleomorphic cells that invade other tissues. "In support of this model, elevated expression of almost every cohesin subunit (RAD21, SMC1A, SMC3, STAG1, PDS5, WAPL) and cohesin regulator (NIPBL, MAU2) appears to be oncogenic and present in a wide range of cancer cells." (PMID 41370327, 2025). "Our observations that Nipbl/Mau2 predominantly binds outside of repair foci seem to strengthen the recent ChIP-based observation that cohesin binds at the border of restriction-enzyme induced γH2AX foci in a human cancer cell line, perhaps limiting the spread of γH2AX along chromosomes." (PMID 24287868, 2014).
MAU2 also shares sentences with these, for which no sentence is quoted: infection (2 papers); lung carcinoma (2); acute pancreatitis (1); adolescent idiopathic scoliosis (1); bipolar disorder (1); Cirrhosis (1); colon cancer (1); coronary heart disease (1); eating disorder (1); Ewing sarcoma (1); genetic diseases (1); lipid metabolism disorders (1); major depressive disorder (1); melanoma (1); mental disorder (1); Multiple Organ Failure (1); myeloid malignancies (1); non-alcoholic fatty liver disease (1); oral cancers (1); psychosis (1); schizophrenia (1); squamous carcinoma (1); tumor (1).